FOXA1 (forkhead box A1)
Diseases named in the same sentence as FOXA1 in open-access papers (continued):
Sharing a sentence is not in itself a finding about the gene and the disease.
prostate carcinoma (continued). "Previous in vitro studies have shown that FOXA1 increases pro-angiogenic factors, including EGF, endothelin-1, and endoglin in prostate cancer cells and promotes endothelial cell proliferation, migration, and tube formation." (PMID 35627227, 2022). "The overexpression of FOXA1 was inversely correlated with IFN signaling activity and antigen-presenting gene expression in prostate cancer patients, contributing to immune escape and conferring resistance to immune checkpoint inhibitors." (PMID 35892678, 2022). "In promoting proliferation in ART, CREB5 exhibited a strong degree of interaction with known AR transcription machinery, including FOXA1, HOXB13, and GRHL2, as well as novel prostate cancer regulators TBX3 and NFIC." (PMID 35550030, 2022). "This close correlation of TBX3 and NFIC dependency with that observed for FOXA1 supports the conclusion that TBX3 and NFIC regulate prostate cancer cell viability in the AR setting." (PMID 35550030, 2022). "In prostate cancer, HOXB13, which is highly expressed in adulthood in the normal prostate, functions as a coregulator of AR, together with FOXA1, to modulate the epigenetic status required for prostate tumorigenesis." (PMID 33514011, 2021). "From the PCA analysis results, we found that the roles of FOXA1, NFYA, and FOXP1 in regulating stemness genes in normal prostate samples were changed by comparing those in prostate cancer samples." (PMID 33985534, 2021). "Topics enriched in Samples 4 and 16 include genes such as AR, GRHL2, FOXA1, SLC43A1, WNT7B, which are known downstream players active in prostate cancers with ERG expression." (PMID 34911933, 2021). "Consistent with the essentiality of FOXA1, the deletion of each CRE of the plexus resulted in significant reduction in FOXA1 mRNA expression and LNCaP prostate cancer cell growth." (PMID 32946061, 2021). "We analysed the levels of FOXA1 and IGFBP-2 in a panel of prostate cancer and normal prostate epithelial cells." (PMID 32655839, 2020). "Nonetheless, three proteins, AR, FOXA1, and HOXB13, are also known to mediate prostate cancer progression, and their enrichment corresponded with u2j." (PMID 33322492, 2020). "We found that there is a striking correlation between the strength of the HOXC4 or HOXC6 binding sites and the strength of the binding sites for the key prostate cancer transcription factors HOXB13, FOXA1, and AR." (PMID 32012197, 2020). "As for ERG, it synergistically regulates by physically interacting with prostate-cancer-specific regulators AR, HOXB13, and FOXA1." (PMID 33299103, 2020). "Using genome-wide CRISPR screens, we profiled over 10,000 FOXA1 and CTCF binding sites for their roles in regulating the fitness of breast and prostate cancer cells, and accordingly developed a model to predict essentiality for cis-elements." (PMID 31727847, 2019). "Using CRISPR/Cas9 knockout screens and gene essentiality or fitness as the readout, we systematically investigated the essentiality of over 10,000 FOXA1 and CTCF binding sites in breast and prostate cancer cells." (PMID 31727847, 2019). "Thus, for instance, FOXA1 (Forkhead box protein A1), another member of the forkhead box protein family, was found bound in the exon 3 region of UBE2C gene and, in association with MED1 (mediator complex subunit 1), was capable of altering UBE2C expression levels in prostate cancer cells." (PMID 29596365, 2018). "Whilst FOXA1 represses AR binding to DNA, GATA2 positively collaborates with the AR in androgen-mediated gene expression in prostate cancer." (PMID 28264478, 2017).
prostate carcinoma (continued). "We propose that the acquisition of AR binding at the enhancer, which triggers a decline in GR expression, is likely a consequence of the reprogrammed AR cistrome in prostate cancer versus normal tissue, which is enriched at HOXB13 and FOXA1 sites." (PMID 28891793, 2017). "Further ChIP-seq analysis in prostate cancer cell lines indicated multiple positive signals in the EcoRI fragment BE8-9 (chr2: 85778503–86781283) including H3K4me1 and FOXA1 in LNCaP; CTCF and FOXA1 in VCaP, and RAD21 in NCIH660." (PMID 26979803, 2016). "As expected, multiple motifs of transcription factors involved in prostate cancer pathobiology were found, including ERG, AR, and its pioneer factor FOXA1 (Table EV1)." (PMID 26412853, 2015). "We also found insignificant correlations of PBOV1 to FOXA1 and androgen receptor genes in GDS1746 prostate cancer dataset." (PMID 23418531, 2013). "FoxA1, also known as hepatocyte nuclear factor HNF-3-alpha, is a key partner for ERα and AR in promoting transcriptional activity in breast and prostate cancer, respectively, and recognizes the FKH motif." (PMID 22383394, 2012). "However, the precise role of FOXA1 in prostate cancer (PC) remains unknown." (PMID 22879989, 2012). "OCT4, a TF that can form complexes with other TFs (e.g., forkhead box protein A1 (FOXA1), androgen receptor (AR), and nuclear respiratory factor 1 (NRF1)), promotes prostate cancer (PCa) progression through epigenetic alterations and acquires chemotherapy resistance." (PMID 40642070, 2025). "We hypothesized that FOXA1 was the PF for HNF4G (and possibly HNF4A), as seen with other NRs in breast and prostate cancer that require FOXA1." (PMID 41168397, 2025). "FOXA1 is also an integral part of the AR interactome in prostate cancers but is not required for AR to bind DNA." (PMID 38317241, 2024). "It should also be noted that while we have drawn a link between FOXA1, AR, and SEMA3C in prostate cancer, a direct causal relationship cannot be concluded without further studies." (PMID 38528115, 2024). "Nonetheless, our data demonstrate that alterations to FOXA1 have functional consequences and may be responsible for altered SEMA3C expression in prostate cancer specimens." (PMID 38528115, 2024). "In addition, FOXA1 overexpression increased the proliferative capacity of AR signaling in MDA-MB-453 breast and LNCaP prostate cancer cell lines." (PMID 38317241, 2024). "The FOXA1 mutant and mutant-negative (control) groups for prostate cancer were selected using genomic data." (PMID 37958805, 2023). "ALAN identified direct protein-protein interactions in prostate cancer (AR, HOXB13, and FOXA1)." (PMID 37059746, 2023). "Likewise, similar outcomes were also observed in liver cancer, nasopharyngeal cancer, gastric cancer, prostate cancer, and colorectal cancer, in which the EMT process seemed to be reversed due to the presence of FOXA1." (PMID 36393971, 2022). "Similarly, for prostate cancer, KDM1A, BRD4, and PRMT1 were depleted in LNCaP cells as well as AR, FOXA1 and NCOA1, thus serving as positive controls." (PMID 35973998, 2022). "Conversely, in prostate cancer, FOXA2 mutations are rare/absent, whereas FOXA1 mutations are common, with diverse experimental evidence that different classes of FOXA1 mutations in prostate cancer are dominant and gain of function." (PMID 35703180, 2022). "Studies also revealed that overexpressed ERG co-opts prostate-specific master regulatory transcription factors, including AR, HOXB13 and FOXA1, in a process facilitated by their physical interaction with ERG and actives NOTCH signaling in primary prostate cancer." (PMID 34630112, 2021). "Conspicuously, in PC-3 cells, UBE2C could recruit FOXA1 to its enhancers, that was mostly likely correlated with the expression of UBE2C and promoted the progression of castration-resistant prostate cancer." (PMID 33630978, 2021).
prostate carcinoma (continued). "For one of the regulatory SNPs, rs684232, we found that the variation altered chromatin binding of transcription factor FOXA1 on the DNA region and led to aberrant gene expression of VPS53, FAM57A, and GEMIN4, which play vital roles in prostate cancer malignancy." (PMID 34445492, 2021). "Among the eight prostate cancer cell lines in the dataset (22Rv1, DU145, LNCaP, MDA-PCa-2B, NCI-H660, PrECLH, PC3, and VCaP), FOXA1 mRNA abundance is above the 90th percentile in all but one cell line (PrECLH) compared with the >56,000 protein coding and non-protein coding genes profiled." (PMID 31974375, 2020). "Interestingly, in the smaller tissue cohort we found a positive correlation between FOXA1 and IGFBP-2 levels (r = 0.319, p = 0.029) in prostate cancer tissue." (PMID 32655839, 2020). "In prostate cancer, CREB5 could improve resistance to enzalutamide with the help of FOXA1 and selectively enhance the interaction of AR with target genes critical for survival." (PMID 32843066, 2020). "Despite the oncogenic roles of FOXA1, therapeutic avenues to inhibit its activity in prostate cancer are lacking." (PMID 31974375, 2020). "However, the region gains enhancer activity in prostate tumors and in the prostate cancer cell line, LNCaP as seen by the presence of DHS, H3K27ac, FOXA1, and AR occupancies." (PMID 32680982, 2020). "We posit that the FOXA1 3′-UTR represents a useful region for liquid biopsy gene panels, since any panel spanning this region will capture ~20% of patients and the detection of UTR indels can help confirm prostate cancer origin for the ctDNA." (PMID 30272002, 2018). "Provocatively, it was found that FOXA1 also has the potential to reprogram GATA2 and act as a pioneering effect for both AR and GATA2, suggesting that FOXA1 regulates a transcriptional network that controls AR-mediated gene expression in prostate cancer." (PMID 29888169, 2018). "A recent study suggested that NONOG, a pluripotency transcription factor, reprograms prostatic cancers to become castration resistant by dynamically repressing and engaging the AR/FOXA1 signaling axis." (PMID 29581876, 2018). "By further integrating with ChIP-seq data, our study is able to refine these candidate SNPs that are overlapped with active histone modifications, and transcription factor binding including FOXA1 and HOXB13, the critical transcription factors during prostate cancer development." (PMID 26979803, 2016). "In contrast, in the human situation, TSPY was predominantly co-expressed with FOXA1 in the epithelial cells of PIN lesions and FOXA1 and another cancer biomarker, AMACR, in the adenocarcinoma cells in clinical prostate cancer samples of various degrees of malignancy." (PMID 24528896, 2014). "Thus, the combined absence of both AR and FOXA1 likely contributes to the heightened levels of GR in AR-negative prostate cancer cells." (PMID 39027480, 2024). "This effort led to the successful generation of seven novel organoid lines harboring prostate-cancer-specific driver alterations, including ETS-translocations, CHD1 loss, and SPOP and FOXA1 mutations-three of which had not been previously represented in 2D prostate cancer cell line models." (PMID 38835365, 2024). "Notably, as most of the approved drugs targeting MAOA and KDM1A were monoamine inhibitors used for mental illness or diabetes, we suggest they have a potential to cure FOXA1 mutant primary prostate cancer without lethal side effects." (PMID 37958805, 2023). "Interestingly, three major subgroups of genomic subcomplexes of AR interaction partners were identified, where FOXA1 and HOXB13, known transcription factors interacting with AR and affecting the AR cistrome in prostate cancer, dictate selective gain of function for AR action." (PMID 34638309, 2021).
prostate carcinoma (continued). "To delineate the CREs that could be actively involved in the transcriptional regulation of FOXA1, we annotated the DHS with available ChIP-seq data for histone modifications and TFs conducted in LNCaP, 22Rv1, VCaP prostate cancer cell lines and primary prostate tumors 18,38." (PMID 31974375, 2020). "Hence, FOXA1 does not regulate all GR and AR binding in prostate cancer cells." (PMID 39027480, 2024). "The results of our study provide evidence that FOXA1 staining level alone is not dramatically associated with risk of BCR after SRT and is therefore relatively unlikely to be of use in improving patient selection for SRT following recurrent prostate cancer after RP." (PMID 26986977, 2016). "This reveals binding sites for several known prostate cancer regulatory TFs, including AR, ERG, ETS1 and FOXA1 in a putative enhancer region that does not belong to the set of GWAS SNPs." (PMID 37971305, 2024). "Using integrated omics profiling, including RNA-seq and thermal proteome profiling, the forkhead box protein A1 (FOXA1) and non-homologous end joining (NHEJ) repair executer Ku70/Ku80 were strongly suggested as direct targets of ivermectin in prostate cancer." (PMID 36050295, 2022). "Aberrant transcription in prostate cancer is not driven solely by AR activity but through the collaborative action of AR enhancers like those of HOXB13 and FOXA1 genes, which modify chromatin structure to facilitate AR and other factors in accessing cancer-specific binding sites." (PMID 39796635, 2024). "We applied integrated profiling, including RNA-seq and Thermal proteome, that found pioneer factor Forkhead Box Protein A1 (FOXA1) and Non-homologous End Joining (NHEJ) repair executer Ku70/Ku80 were strongly suggested as the direct target of ivermectin in prostate cancer." (PMID 36050295, 2022). "We note that we also found peptides from LBD1 and DNMT1, but further evaluation showed that these proteins did not exhibit as strong a difference in AR-expressing prostate cancer cells, and we therefore concentrated on NFIC and TBX3, which also interacted with FOXA1 in our other RIME experiments." (PMID 35550030, 2022). "In prostate cancer, for example, (+)-JQ1, but not (−)-JQ1, significantly inhibited cancer growth but promoted invasion and metastasis through its direct interaction and inhibition of forkhead box protein A1 (FOXA1), an invasion suppressor in prostate cancer, independent of any BET proteins." (PMID 37296583, 2023).
lung cancer (63 papers, 2012 to 2025). A malignant neoplasm involving the lung. "Specifically, FOXA1 contributes to the loss of epithelial characteristics and enhances the invasion and metastasis of lung cancer cells by regulating the expression of ECM-related genes." (PMID 39551792, 2024). "To further elucidate the underlying mechanism of S1PR1’s regulation of FOXA1, we conducted a comprehensive search using Targetscan, miRTarbase, and miRDB databases to identify the microRNAs (miRNAs) that modulate FOXA1 in lung cancer tissues or cells." (PMID 39551792, 2024). "A study of nonsmall cell lung cancer found that FOXA1 siRNA transfection caused G0/G1 phase cell cycle arrest and reduced the invasion, migration, and proliferation abilities of A549 cells." (PMID 35968505, 2022). "Overall, these results revealed that the role of cooperation between PGC1α and FOXA1 on the transcription of ID1 is functionally linked to TGFβ1-mediated EMT in lung cancer cells." (PMID 35897813, 2022). "As FOXA1 was implicated during EMT in lung cancer, we examined which functions FOXA1 was likely to regulate." (PMID 24093963, 2013). "High expressions of FoxA1 and FoxA3 in lung cancer were related with poor overall survival, whereas FoxA2 overexpression was associated with a better overall survival, suggesting the opposing roles between FoxA1/A3 and FoxA2 in the carcinogenesis." (PMID 32151057, 2020). "Interestingly, the precise consequences of FoxA1/2 loss in lung cancer are highly dependent on the specific context in which it occurs (model)." (PMID 30475207, 2018). "This study further analyzed the expression and prognostic significance of FOXA1 in lung cancer patient tissues, discovering that patients with positive FOXA1 expression exhibited poorer prognoses compared to those negative for FOXA1." (PMID 39440051, 2024). "Functional and mechanistic investigations have confirmed that FOXA1 promotes lung cancer cell proliferation and inhibits apoptosis by modulating the PI3K/AKT signaling pathway and its downstream effectors involved in the cell cycle and apoptosis." (PMID 39440051, 2024). "Correlation analysis revealed a positive association between FOXA1 and HER2 expression in lung cancer (r = 0.5398, P < 0.0001), confirming the findings at the histological level." (PMID 39440051, 2024). "FOXA1 is a transcription factor that affects organogenesis and cancer progression in various cancers such as breast, prostate, endometrium, liver, and lung cancers." (PMID 39000600, 2024). "Our results demonstrate that RC48 not only reduces HER2 protein levels in lung cancer cells but also decreases FOXA1 protein expression." (PMID 39440051, 2024). "Previous research has established FOXA1's critical role in lung cancer progression, particularly in non-small cell lung cancer (NSCLC), where it enhances proliferation, invasion, migration, and diminishes chemosensitivity." (PMID 39440051, 2024). "Our findings revealed that in lung cancer tissues or cells, five transcription factors—FOXA1, CEBPB, CTCF, LMNB1, and POLR2A—concurrently regulate the transcription of COL5A1, MMP1, and SERPINE1." (PMID 39551792, 2024). "High expression of FOXA1 has been observed in acute myeloid leukemia, thyroid cancer, bladder cancer, esophageal cancer, and lung cancer, indicating its role in promoting tumor proliferation, invasion, and migration." (PMID 38886389, 2024). "Remarkably, 66.67% of lung cancer tissue samples showed positive FOXA1 expression, indicating a substantial increase in its levels." (PMID 39440051, 2024). "In this study, we investigated the essentiality of FOXA1 across cell line lineages and identified a subset of non–small cell lung cancer (NSCLC) cell lines that is FOXA1 dependent." (PMID 37691854, 2023). "To ensure that the antiproliferative effects of ORIC-101 were specifically mediated by GR inhibition, we tested ORIC-101 in GR-negative HT-29 colon cancer cells and FOXA1-independent A549 lung cancer cells." (PMID 37691854, 2023).